PALB2 (partner and localizer of BRCA2)
Diseases named in the same sentence as PALB2 in open-access papers (continued):
Sharing a sentence is not in itself a finding about the gene and the disease.
cancer (continued). "Following large-scale cancer sequence analysis, many other HRD-related genes (CDK12, ATM, PALB2) were commonly found in mCRPC, and these non-BRCA DNA repair genes could be used as alternative biomarkers to predict the sensitivity of PARP inhibitors." (PMID 34975480, 2021). "A similar enrichment for signature 3 was found for PALB2 and RAD51C mutations or epigenetic silencing of the BRCA1 or RAD51C promoter, but not for inactivation of other cancer-associated genes, such as CHEK2 and ATM." (PMID 33670893, 2021). "The genes preferentially mutated in metastases were MYLK, PEAK1, SLC2A4RG, EVC2, XIRP2, PALB2, and ESR1 (five of which are not significantly mutated in any type of human primary cancer)." (PMID 34771579, 2021). "PALB2, an important member of the HRR pathway, is frequently observed in cancer." (PMID 35087742, 2021). "As in BRCA1/2 mutation carriers, the lack of both PALB2 alleles causes the activation of the NHEJ with a consequent genomic instability and cancer cell death." (PMID 33800556, 2021). "The “synthetic lethality” offer a promising opportunity to develop novel therapy in terms of personalized medicine in cancer, such as PARP inhibitors; nonetheless, PALB2 advantages for development of a specific therapeutic strategy such as PARP inhibitors is still not clear." (PMID 30975222, 2019). "Recent studies demonstrated that RAD52 has an important role in genomic stability maintenance and cancer suppression in mammalian cells, while several HR proteins including BRCA1, BRCA2, PALB2, and RAD51 paralogs (RAD51B, C, D, and XRCC 2 and 3) present an inactivated and depleted activity." (PMID 31652722, 2019). "Nonsense and frameshift mutations, particularly in exon 11 of the PALB2 gene, result in a variety of premature stop codons and ultimately a truncated PALB2 protein, which is exceedingly rare in the general population and those without cancer." (PMID 24624093, 2014). "Notable is that her personal history of cancer does not match any of the cases that appear in the pedigrees of PALB2 p.Q775X positive French Canadian cancer families described thus far (including the new carrier family identified in this study)." (PMID 23302520, 2013). "Interestingly, PALB2 has a close interaction with BRCA1 and BRCA2, which could lead to malignant tumors." (PMID 40507905, 2025). "When homologous recombination repair genes BRCA1/2, ATM, PALB2, and CHEK2 are inactive, a variety of error-prone and non-conservative DNA repair pathways are used, increasing the incidence of cancer and worsening its prognosis while also causing genomic instability." (PMID 37732318, 2023). "Of patients who did not have a positive family history of any cancer (n = 487), 57 deleterious variants were detected in 54 patients, including BRCA2 (40.4%, 23/57), BRCA1 (22.8%, 13/57), PALB2 (10.5%, 6/57), NBN (5.3%, 3/57), MRE11A (5.3%, 3/57) and other genes (15.8%, 9/57)." (PMID 36232564, 2022). "The mutagenic processes result from loss of integral HR pathway components; therefore, cancers with non-BRCA HR defects, such as germline or somatic mutations in PALB2, RAD51B, RAD51C, or RAD51D, or their inactivation through promoter methylation, would also receive a positive treatment prediction." (PMID 31727117, 2019). "In addition, a number of non-rare variants in genes relevant to cancer risk (e.g. in BRCA1, PALB2, BLM, and others) were detected in a significant number of individuals." (PMID 26485759, 2015).
cancer (continued). "Thus, developing therapeutic strategies targeting RAD52 to treat PALB2, BRCA1 or BRCA2 mutant cancers might be considered." (PMID 26610585, 2015). "Therefore, we aimed to investigate the PALB2/LP variant prevalence and mutational spectrum in the Hungarian HBOC patients, including 191 very young cases, to compare it to patients with non-HBOC tumor types and to a healthy, non-cancer control population." (PMID 37686625, 2023). "Notably, when STRING network analysis was used to investigate functional interactions, this revealed a DDR cluster that included BRCA1 and BRCA2, as well as their interacting tumour suppressor partners PALB2 and BAP1, two cancer-associated DDR genes not previously indicated as G4 ligand sensitisers." (PMID 31287417, 2019). "Overall, our results point to BRCA2, but not PALB2, as being important for the maintenance of HAC in HT1080 cancer cells." (PMID 39893637, 2025). "Although BRCA1/2 is the most common genetic variant detected on germline testing, it is prudent to recognise non-BRCA HRR-related genes such as PALB2, ATM and RAD51 can also contribute to HBOC and other carcinomas." (PMID 39796639, 2024). "This group included 66 (22.7%) with a known PDAC PGV (54 BRCA2, 5 PALB2, 5 ATM, 2 BRCA1) previously identified outside the MDPC on the basis of personal or family history of other cancer diagnoses, but no known PDAC family history." (PMID 35906821, 2022). "Among them, the most frequent were reported in PALB2 and CHEK2, further confirming their involvement in some non-BRCA cancers." (PMID 31936873, 2020). "Interestingly, when the same panel of 94 cancer genes was examined in the group of TNBC BRCA-negative patients from Cyprus, germline PVs of the PALB2 gene were found in older women but not in young." (PMID 37791908, 2023). "In our study we did not have sufficient numbers of cancers with BRCA1, PALB2, or other rare HRR gene alterations to determine whether DARC Sign would assign BRCA2d status to such cancers." (PMID 36914848, 2023). "From the genes evaluated here, BRCA1, BRCA2, and PALB2 are part of the ACMG Secondary Findings v3.0 list and laboratories are now recommended to report GPV in these genes even in individuals without a personal or family history of cancer when next generation sequencing is performed." (PMID 35805029, 2022).
tumor (246 papers, 2011 to 2026). "Pathogenic mutations in PALB2 (T351fs*9) were present, which play critical roles in the DNA repair and tumor suppressor pathways." (PMID 40491286, 2026). "In Cohort A, comprised of patients with core HRD (BRCA1/2 or PALB2 mutations), we observed high tumor response rates, durable disease control, and encouraging long-term survival." (PMID 40951294, 2025). "Disruption of PALB2’s structure leads to genomic instability by impairing HR repair, thereby elevating the tumor mutational burden." (PMID 40040726, 2025). "Impaired HR through mutations in BRCA1, BRCA2, PALB2, or potentially other mechanisms, can increase the rate of point mutations and random insertions and deletions, promoting tumor neoantigen formation and presentation, and cytotoxic T-cell infiltration." (PMID 40426860, 2025). "Altogether, this demonstrates the potential of our combinational therapy PADtal and its therapeutic advantage over PADola in suppressing BRCA2 and PALB2‐deficient tumor growth in vivo." (PMID 40823818, 2025). "HR deficiency is often driven by loss of BRCA1, BRCA2 or PALB2 function in tumor cells, which is the result of inactivating mutations and LOH." (PMID 38589664, 2024). "The CARRIERS study showed that the contralateral BC risk in PALB2 carriers was only statistically higher in HR− patients, highlighting the importance of tumor phenotype in genetic counseling." (PMID 39741970, 2024). "This study analyzing BRCA1, BRCA2, and PALB2 mutations through tumor-targeted sequencing boosts several notable strengths." (PMID 38098088, 2023). "If a patient was identified with any P/LP variants of BRCA1, BRCA2, or PALB2 within the tumor, clinical germline testing (CGT) would be performed." (PMID 38098088, 2023). "Patients with PALB2 mutations have more aggressive clinical and pathological features of the tumor process." (PMID 37628606, 2023). "PARPi showed anti-tumor activity in this patient with a PALB2 mutation, further supporting previous studies." (PMID 37173992, 2023). "Among DNA repair genes, we detected evidence of positive selection in the tumor suppressor-encoding PALB2 and in four DNA polymerase-encoding genes (POLA1, POLD1, POLK, and POLM)." (PMID 37728212, 2023). "Among the six patients who received PARPi therapy, one had a tumor with a PALB2 mutation other than BRCA and had a clinical partial response." (PMID 37173992, 2023). "It has been observed that PALB2 associated tumours are sensitive to platinum-based chemotherapy and PARP inhibitors." (PMID 36010882, 2022). "Such approaches have been shown to be efficacious in treatment of breast and ovarian cancers of BRCA1/2 carriers, as well pancreatic cancers with an inactivation of BRCA1, BRCA2, or PALB2 and an HR deficiency tumor mutation signature." (PMID 36497436, 2022). "PALB2 is a tumor suppressor in which inherited mutations increase the risk of breast, ovarian, pancreatic, and other cancers." (PMID 35404932, 2022). "We observed that both BARD1- and PALB2-mutant cases had significantly higher median HRD scores than WT tumors (p = 0.023 and p = 0.041, respectively), consistent with alterations in PALB2 or BARD1 conferring tumor HR deficiency." (PMID 35768576, 2022). "The PTVs in BRCA2, CHEK2, and PALB2 were associated with larger tumor size, lymph node involvement, and higher stage at diagnosis (eFigure 1 in Supplement 1)." (PMID 35084436, 2022). "AA patients with pathogenic variants in BRCA2 or PALB2 were 11 times more likely to be diagnosed with TNBC versus another tumor subtype than were EA patients with pathogenic variants in either of these genes (P = 0.001)." (PMID 33479248, 2021). "One patient with two deleterious PALB2 mutations, one in exon 4, c.1653T>A, and another in exon 6, c.2576C>G, was administered with olaparib and showed a 70% reduction in the tumor burden." (PMID 34439348, 2021).
tumor (continued). "CABR95, carrying the germline pathogenic PALB2 mutation enriched in the tumor by somatic LOH, had a high mean homologous recombination deficiency (HRD) score, in keeping with the expected effects of loss-of-function of this gene." (PMID 32295625, 2020). "LOH or AST mutation was detected in at least one tumor with PALB2, ATM, RAD51D, BARD1, BRIP1, RAD51C, or NF1 germline mutation." (PMID 32566746, 2020). "ABC patients with somatic PALB2 mutations had high tumor mutation burden (TMB), while germline mutant patients exhibited low (even U) TMB." (PMID 33193564, 2020). "Responses in tumours with PALB2 mutations were frequent, although the low prevalence of these mutations means that further data are required to confirm these findings." (PMID 31806540, 2020). "Proteins encoded by these three tumor susceptibility genes (PALB2, BRCA1, BRCA2) cooperate in the BRCA pathway by forming a complex, which is essential for HR repair." (PMID 31877165, 2019). "In order to gain a better understanding regarding the pathogenicity of variants of uncertain significance (VUS) in the PALB2 tumor suppressor gene, a global functional analysis of variants was undertaken." (PMID 31586400, 2019). "This suggests that protein instability due to LOF variants in tumor suppressor genes, including PALB2, constitutes a mechanism of pathogenicity." (PMID 31757951, 2019). "The tumour phenotypes associated with PALB2 tumours are very similar to those associated with BRCA2 tumours, with 61% of invasive tumours having associated DCIS." (PMID 31060593, 2019). "A PALB2 p.E672Q variant (Polyphen score 0.275) was present in one tumor and a deleterious PALB2 p.G998E variant found in another (Polyphen score 1)." (PMID 31346352, 2019). "In several of the cases described by Sahasrabudhe and colleagues, tumour molecular profiling was done and showed that carriers of PALB2 mutations had mutational signatures indicative of defects in homologous recombination." (PMID 29706558, 2018). "PALB2 germline truncating variants associated with BC display an aggressive tumor phenotype, showing higher tumor grade and also higher levels of the proliferation marker protein Ki-67." (PMID 28858227, 2017). "These variants are hence unable to fulfil PALB2 tumour suppressor function, even in the presence of a wild-type allele." (PMID 29387807, 2017). "We examined the effect of Palb2 heterozygosity on the tumor predisposition of Brca2G25R/Ko animals that had a mean survival time of 80 weeks." (PMID 27490902, 2016). "We found variable methylation in tumor-derived DNA at two PALB2 promoter-associated CpG probes (cg08762306 and cg05002041)." (PMID 27902704, 2016). "Since PALB2 mutations are rare, the contribution to the increased risk for these tumour types should be limited in the study cohort." (PMID 26082817, 2015). "The results showed the PALB2-inactivated tumours to have a predominantly HR-deficient signature (GEL-Ovary_common_SBS3), whereas the ATM-inactivated tumours had a lesser HR-deficiency signature with others (i.e. GEL-Ovary_common_SBS5 and GEL-Ovary_common_SBS1+18) appearing more prominent." (PMID 39794353, 2025). "In PALB2-mutated case P-T1, the anti-PALB2-N-terminus antibody immunofluorescence labeling signal was present at a high intensity level in cytosol and at medium and homogeneous intensity in the nuclei of tumor cells." (PMID 40868059, 2025). "This patient’s tumor had a presumably deleterious PALB2 K1124* mutation." (PMID 41145467, 2025). "New investigations showed germline PALB2 mutations in BC families, indicating that PALB2 could serve as an FBC tumor suppressor." (PMID 39390525, 2024). "These variants were predominantly specific to individual tumours, except for missense mutations detected in PALB2 (c.1651T>A; p.Tyr551Asn) and in CHEK2 (c.1261A>C; p.Thr421Pro), which were observed in 13 and 130 specimens, respectively, resulting in a high mutation burden, particularly for CHEK2." (PMID 37373225, 2023).
tumor (continued). "RAD51 can accurately identify all PALB2-mutated tumours as HR-deficient in clinical breast samples." (PMID 36010882, 2022). "Analyses of mouse mammary glands and cultured human cells showed that combined loss of BRCA1 and PALB2 led to high levels of reactive oxygen species (ROS) and increased apoptosis, implicating oxidative stress in the delayed tumor development in Brca1;Palb2 double CKO mice." (PMID 33893322, 2021). "More extensive tumour studies could potentially have been revealing in delineating the contribution of the PALB2 variant in these GISTs." (PMID 33854214, 2021). "In BRCA1/PALB2 mutated tumors, carboplatin was the most active drug in reducing tumor volume." (PMID 33782404, 2021). "Reversions have not only been detected in tumours with BRCAm but also in tumours with mutations in other HRR genes such as PALB2, RAD51C and RAD51D, which reinforces the notion that mutations outside of BRCA genes that impact HRR are valid selection biomarkers for PARPi therapy." (PMID 35008208, 2021). "We confirmed associations of BARD1 and PALB2 with the triple-negative subtype and ASTs, and found significant loss-of-function mutations on the wildtype allele of genes with germline mutations in the tumor samples." (PMID 32566746, 2020). "Regarding the therapeutic approach, these relevant mutations may be used for drug selection: for PALB2 mutations, a response of the tumours has been registered for PARP inhibitors, mitomycin C and platinum compounds." (PMID 32756499, 2020). "For this reason we were able to identify two additional tumor cases with mutations in other DNA damage response genes than BRCA1/2 (PALB2 and NBN), which might also respond to PARP-inhibitor therapy." (PMID 31029168, 2019). "Though BRCA and PALB2 mutations were relatively uncommon, tumors from BRCA- and PALB2-mutated patients had distinct mutational profiles compared to non-mutated patients, were more likely to be PD-L1 positive, and had a comparatively high tumor mutational burden (TMB)." (PMID 35205643, 2022). "Upon combined loss of BRCA1 and PALB2, massive apoptosis may occur due to excessively high ROS levels, despite further NFκB activation, leading to the loss of potential tumor-initiating cells and delayed tumor development." (PMID 33893322, 2021). "Notably, deletion of Palb2 caused the highest penetrance of both mammary and overall tumor development, implying that the loss of PALB2 may strike the best balance between genome instability and cell fitness that allows the most efficient tumor development." (PMID 33893322, 2021). "To assess DNA repair pathways essential for the tumor cells and contributing to sensitivity/resistance of the tumor cells to BETi, we use ex vivo functional RNAi screening to discover biological insights on the different DNA repair pathways with the PALB2 deficient cells." (PMID 34084283, 2021). "In our study, high HRD scores could be explained in almost every case by tumor histology and molecular classification (invasive medullary carcinoma or TNBC) or by the presence of a tumor-enriched germline variant in a gene implicated in homologous recombination (PALB2 in CABR95)." (PMID 32295625, 2020). "The findings largely validated previous reports highlighting the importance of tumor suppressor genes such as ATM, BRCA1, BRCA2, and PALB2 for a limited number of tumor types." (PMID 40072281, 2025). "A tumor grade was reported for 39 (78.0%) PALB2 GPV carriers; grade 1 five times (12.8%), grade 2 twenty-one times (53.8%), and grade 3 thirteen times (33.3%)." (PMID 40428378, 2025).